RNU6-238P (RNA, U6 small nuclear 238, pseudogene)
Gene: Small nuclear RNA gene on chromosome 12 (50,656,973 to 50,657,078, forward strand). Ensembl gene ENSG00000200183.
Homologues: Orthologues: chimpanzee U6 (99% identical), macaque U6 (94% identical), mouse Gm26131 (90% identical), rat LOC120095354 (83% identical), guinea pig U6 (69% identical). Paralogues in human: RNU6-727P (91% identical), RNU6-43P (90% identical), RNU6-1309P (89% identical), RNU6-11P (88% identical), RNU6-1243P (88% identical), RNU6-22P (88% identical), RNU6-24P (88% identical), RNU6-37P (88% identical), RNU6-1094P (87% identical), RNU6-137P (87% identical), RNU6-17P (87% identical), RNU6-18P (87% identical), and 1286 more.